GHET1 (gastric carcinoma proliferation enhancing transcript 1)
Diseases named in the same sentence as GHET1 in open-access papers (continued):
Sharing a sentence is not in itself a finding about the gene and the disease.
ovarian carcinoma (4 papers, 2019 to 2021). A malignant neoplasm originating from the surface ovarian epithelium. "Since the GHET1 function in ovarian cancer cells has been only examined by in vitro assays, in vivo analyses of GHET1 are needed." (PMID 33996797, 2021). "The lncRNA GHET1 is upregulated in ovarian cancer and higher expression correlates with increased tumor size and distant metastasis." (PMID 33996797, 2021). "In ovarian cancer, gastric carcinoma high expressed transcript 1 (GHET1) interacts with the E3 ubiquitin ligase von Hippel-Lindau (VHL)." (PMID 33652661, 2021). "Overexpression of GHET1 significantly enhanced the glucose consumption and lactate production of both A2780 and SKOV3 cells, which indicated that overexpression of GHET1 promoted the glycolysis of ovarian cancer cells." (PMID 30988076, 2019). "To further characterize the underlying molecular mechanisms by which GHET1 modulated the growth of ovarian cancer cells, we screened the potential binding partners of GHET1 with the RNA pull-down and mass spectrometry analysis." (PMID 30988076, 2019). "Overexpression of GHET1 promoted the glycolysis of ovarian cancer cells via modulating VHL-mediated degradation of HIF1α." (PMID 30988076, 2019). "As GHET1 regulated the expression of HIF1α, we further detected the effect of GHET1 on the glycolysis of ovarian cancer cells." (PMID 30988076, 2019). "In the present study, we characterized that GHET1 was highly expressed in ovarian cancer tissues and cell lines, which promoted the proliferation of ovarian cancer cells." (PMID 30988076, 2019). "Collectively, our results suggested the oncogenic function of GHET1 via up-regulating the glycolysis in ovarian cancer and can be considered as a promising anti-cancer target." (PMID 30988076, 2019). "Up-regulation of GHET1 was positively correlated with increased tumor size and distant metastasis of ovarian cancer." (PMID 30988076, 2019). "Enhanced expression of GHET1 significantly promoted the proliferation and colony formation of ovarian cancer cells." (PMID 30988076, 2019). "Considering the inhibitory effect of depleted GHET1 on the growth of ovarian cancer cells, we then examined the function of GHET1 in regulating the apoptosis of ovarian cancer cells." (PMID 30988076, 2019). "Compared with the normal tissues, the expression of GHET1 was significantly enhanced in ovarian cancer tissues." (PMID 30988076, 2019). "Up-regulation of GHET1 was positively correlated with the tumor size and metastasis of the ovarian cancer patients." (PMID 30988076, 2019). "In the present study, we found that the long non-coding RNA gastric carcinoma high expressed transcript 1 (GHET1) was overexpressed in ovarian cancer tissues and cell lines." (PMID 30988076, 2019). "Since GHET1 was overexpressed in ovarian cancers, we next investigated the influence of GHET1 on the growth of ovarian cancer cells." (PMID 30988076, 2019). "In conclusion, our results found that GHET1 was highly expressed in ovarian cancer tissues and correlated with the progressed condition of cancer patients." (PMID 30988076, 2019). "The result showed that the level of GHET1 was significantly increased in ovarian cancer cells (OVCAR3, SKOV3, 3AO and A2780) in comparison with that of the HOSEpiC." (PMID 30988076, 2019). "A previous study revealed that lncRNA GHET1 could promote the proliferation of ovarian cancer cells via enhancing glycolysis." (PMID 34372865, 2021). "Furthermore, lncRNA gastric carcinoma high expressed transcript 1 (GHET1) is overexpressed in ovarian cancers and it is positively correlated with the tumor size and metastasis in patients." (PMID 33652661, 2021). "Furthermore, the expression of GHET1 was also detected in several ovarian cancer cell lines and normal ovarian epithelial cells." (PMID 30988076, 2019). "In the present study, we showed that GHET1 was highly expressed in ovarian cancer tissues." (PMID 30988076, 2019).
ovarian carcinoma (continued). "Additionally, the effect of GHET1 on the migration of ovarian cancer cells was also examined with the in vitro would-healing assay." (PMID 30988076, 2019). "In vivo studies that might support the potential oncogenic function of GHET1 in ovarian cancer are necessary in further investigations." (PMID 30988076, 2019). "Overexpression of GHET1 promoted the proliferation of ovarian cancer cell." (PMID 30988076, 2019). "The result indicated the potential promotion effect of GHET1 on the EMT of ovarian cancer cells." (PMID 30988076, 2019). "In this study, our data uncovered that GHET1 contributed to the glycolysis of ovarian cancer cells." (PMID 30988076, 2019). "VHL was detected in the immunoprecipitation complex with GHET1, which suggested the interaction between GHET1 and VHL in ovarian cancer cells." (PMID 30988076, 2019). "In the present study, we identified GHET1 as a novel binding partner of VHL, which consequently promoted the protein stability of HIF1α and enhanced the glucose metabolism of ovarian cancer cells." (PMID 30988076, 2019). "Mechanistically, GHET1 interacted with VHL, the E3 ubiquitin ligase of HIF1α, which blocked the binding between VHL and HIF1α in ovarian cancer cells." (PMID 30988076, 2019). "The molecular study uncovered that GHET1 interacted with VHL and blocked the binding between VHL and HIF1α, which led to the stabilization of HIF1α and up-regulation of glycolysis of ovarian cancer cells." (PMID 30988076, 2019). "The influence of depleted GHET1 on the proliferation of ovarian cancer cells was detected by the MTT assay, which showed that down-regulation of GHET1 significantly suppressed the proliferation of ovarian cancer cells." (PMID 30988076, 2019). "Of note, GHET1 was found to interact with the E3 ubiquitin ligase von Hippel-Lindau (VHL), which consequently blocked VHL-mediated degradation of hypoxia-inducible factor-1α (HIF1α) and enhanced the protein level of HIF1α in ovarian cancer cells." (PMID 30988076, 2019). "However, the expression and function of GHET1 in ovarian cancer have not been demonstrated." (PMID 30988076, 2019).
esophageal cancer (3 papers, 2020 to 2023). A primary or metastatic malignant neoplasm involving the esophagus. "There is evidence that esophageal cancers have higher levels of H3K27Ac in the CCAT1 promoter region, which may explain the increased expression of CCAT1, and the increased H3K27 acetylation level in the GHET1 promoter region in liver cancer may be the cause of the increased GHET1 expression." (PMID 37669935, 2023).
lymph node metastasis (3 papers, 2019 to 2021). "The elevated GHET1 expression was also associated with lymph node metastasis (LNM) (HR = 2.44, 95% CI: 1.86–3.20, p < 0.001) in Chinese cancer patients." (PMID 31885739, 2019). "The elevated GHET1 levels were also associated with lymph node metastases (HR = 2.44, 95% CI: 1.86–3.20, p < 0.001)." (PMID 31885739, 2019). "Six of the seven articles were focused on the association of GHET1 with lymph node metastasis and tumor progression." (PMID 31885739, 2019). "High expression of GHET1 was associated with lymph node metastasis, differentiation, and TNM stage." (PMID 33842553, 2021). "High expression of GHET1 was associated with advanced clinical stage (I–IIA vs IIB–IV, P<0.001), lymph node metastasis (absent vs present, P<0.001), distant metastasis (absent vs present vs, P=0.010) and poor histological grade (well vs moderately/poorly, P=0.003)." (PMID 30948501, 2019).
non-small cell lung carcinoma (3 papers, 2019 to 2021). A group of at least three distinct histological types of lung cancer, including non-small cell squamous cell carcinoma, adenocarcinoma, and large cell carcinoma. "For example, Shen reported that in non-small cell lung cancer, lncRNA GHET1 is associated with the survival of patients." (PMID 31792655, 2020). "A recent study concluded that lncRNA GHET1 promotes cell invasion and proliferation in non-small cell lung cancer by regulating the LATS1/YAP signaling pathway, the findings of which were consistent with our study." (PMID 34401209, 2021). "Similar results in non-small cell lung cancer, patients with high GHET1 expression had short overall survival time and high GHET1 expression was an independent unfavorable prognostic predictor for overall survival." (PMID 30948501, 2019).
prostate carcinoma (3 papers, 2020 to 2022). A carcinoma that arises from epithelial cells of the prostate gland. "LncRNA GHET1 reduces KLF2 expression to trigger HIF-1α/Notch1 signaling in increasing prostate cancer progression." (PMID 35773731, 2022). "Notably, silencing GHET1 promotes KLF2 expression, leading to HIF-1α/Notch1 inhibition and subsequent decrease in prostate cancer progression." (PMID 35773731, 2022).
triple-negative breast carcinoma (3 papers, 2021 to 2023). An invasive breast carcinoma which is negative for expression of estrogen receptor (ER), progesterone receptor (PR), and human epidermal growth factor receptor 2 (HER2). "This study was to assess the specific impacts and mechanism of lncRNA GHET1 in the development of triple-negative breast cancer (TNBC)." (PMID 33869194, 2021). "Similarly, in triple-negative breast cancer (TNBC), hypoxia induces lncRNA GHET1, and lncRNA GHET1 knockdown reduces HIF-1α phosphorylation under hypoxic conditions, retaining YAP in the cytoplasm." (PMID 35071016, 2021).
colon cancer (2 papers, 2019 to 2021). "Herein, the effect of PITX2 and lncRNA GHET1 on the proliferation, migration and invasion of colon cancer cells was evaluated, in the hope of providing novel targets and strategies for colon cancer." (PMID 34372865, 2021). "Herein, the expression of these proteins was found to be upregulated in colon cancer cells following lncRNA GHET1 overexpression." (PMID 34372865, 2021). "The current study suggested that PITX2 could promote the proliferation, migration and invasion of colon cancer cells via enhancing the expression of lncRNA GHET1." (PMID 34372865, 2021). "However, due to the limitation of time and funds, we have only based on SW480 cells to explore the PITX2 and lncRNA GHET1 regulated colon cancer progression." (PMID 34372865, 2021). "The findings of the present study suggested that PITX2 could enhance the proliferation, migration and invasion abilities of colon cancer cells via upregulating lncRNA GHET1 and activating the Wnt/β-catenin pathway." (PMID 34372865, 2021). "lncRNA GHET1 was upregulated in colon cancer cells compared with colonic epithelial cells." (PMID 34372865, 2021). "However, whether PITX2 can affect the development of colon cancer via regulating the expression of lncRNA GHET1 remains unclear." (PMID 34372865, 2021). "Furthermore, lncRNA GHET1 overexpression could activate the Wnt/β-catenin pathway, thus promoting the proliferation and invasion of colon cancer cells." (PMID 34372865, 2021). "Furthermore, the expression levels of lncRNA GHET1 were measured in colon cancer cells." (PMID 34372865, 2021). "Therefore, the current study hypothesized that PITX2 could activate the Wnt/β-catenin pathway via regulating the expression of lncRNA GHET1 to promote the occurrence and development of colon cancer." (PMID 34372865, 2021). "Similarly, Transwell and wound healing assays revealed that the overexpression of lncRNA GHET1 relieved the PITX2 silencing-mediated reduced migration and invasion abilities of colon cancer cells." (PMID 34372865, 2021). "Furthermore, lncRNA GHET1 overexpression abrogated the PITX2 silencing-mediated decreased proliferation, migration and invasion abilities of colon cancer cells." (PMID 34372865, 2021).
high blood pressure (1 paper, 2023). "Further, lncRNA GHET1 has effects in development of pre-eclampsia, a difficult pregnancy indicated by high blood pressure." (PMID 37093889, 2023).
metastasis (1 paper, 2019). The spread or migration of cancer cells from one part of the body (where they first appeared) to another. "In addition, the elevated lncRNA GHET1 expression was also significantly related to more advanced clinical stage, earlier lymph node metastasis, earlier distant metastasis and bigger tumour size." (PMID 31251476, 2019).
tumor (19 papers, 2015 to 2022). "Collectively, lncRNA GHET1 is associated with the tumor development, and the specific mechanism has also been investigated in our study." (PMID 33869194, 2021). "The pooled data illustrated that GHET1 overexpression was significantly associated with larger tumor size, positive lymph node metastasis, positive distant metastasis, and advanced TNM stage." (PMID 32280301, 2020). "In conclusion, the higher lncRNA GHET1 expression was associated with more advanced clinical stage, earlier lymph node metastasis, earlier distant metastasis, bigger tumour size and poorer OS in cancer patients." (PMID 31251476, 2019). "In addition, as bone spreading is also an important clinical feature related to tumor progression and prognosis, the role of lncRNA GHET1 in tumor-associated bone skeletal diffusion can be studied in the future." (PMID 32908508, 2020). "In addition, high expression of lncRNA GHET1 was found to be associated with larger tumor size, poor histological grade, high tumor stage, lymph node metastasis, and distant metastasis." (PMID 32908508, 2020). "We discovered that, compared with low lncRNA GHET1 expression, high lncRNA GHET1 expression was associated with worse OS and several clinicopathological features, including tumor size, differentiation, distant metastasis, lymph node metastasis and clinical stage." (PMID 31227613, 2019). "The combined results indicate that an elevated GHET1 expression level is significantly associated with poor overall survival (OS) (HR = 2.40, 95% CI: 1.87–3.08, p < 0.001) and tumor progression (III/IV vs. I/II: HR = 1.80, 95% CI: 1.48–2.18, p < 0.001) in multiple cancers." (PMID 31885739, 2019). "They conclude that GHET1 contributes to the tumor progression and may be used as a novel diagnostic BC marker." (PMID 29165379, 2017). "The results of tumorigenesis in nude mice 4 weeks later and at the other time points showed markedly decreased tumor volume and weight after knockdown of lncRNA GHET1, while the opposite change occurred after the overexpression of lncRNA GHET1." (PMID 33869194, 2021). "A marked reduction of lncRNA GHET1 in tumor tissues after knockdown of lncRNA GHET1 and a markedly increased one after overexpression of lncRNA GHET1 were confirmed in the qRT-PCR results." (PMID 33869194, 2021). "And the results showed that knockdown of lncRNA GHET1 expression significantly reduced the tumor volume and weight, while overexpression of this gene promoted the tumor development." (PMID 33869194, 2021). "The oncogenic lncRNA gastric carcinoma proliferation-enhancing transcript 1 (GHET1) is upregulated in BC tissues, where its level is associated with tumor size, higher tumor stage, lymph node involvement, and adverse prognosis." (PMID 32756406, 2020). "As a result, lncRNA GHET1 can be used as a promising biomarker to predict tumor metastasis and prognosis in cancer patients." (PMID 32908508, 2020). "The combined results indicated that elevated GHET1 expression levels were significantly correlated with poor OS (HR = 2.40, 95% CI: 1.87–3.08, p < 0.001) and tumor progression in multiple cancers (III/IV vs. I/II: HR = 1.80, 95% CI: 1.48–2.18, p < 0.001)." (PMID 31885739, 2019). "The purpose of this meta-analysis was to analyze existing data to reveal potential clinical applications of GHET1 for cancer prognosis and tumor progression." (PMID 31885739, 2019). "The downregulation of GHET1 in combination-treated GC cells suggested that ACBP and ASLB synergistically suppressed GHET1 expression and subsequently acted in tumor cell proliferation." (PMID 29156779, 2017). "Since both PITX2 and lncRNA GHET1 could promote the proliferation of tumor cells via activating Wnt/β-catenin signaling, the current study hypothesized that both molecules could interact with each other." (PMID 34372865, 2021).
tumor (continued). "An increasing number of studies have been carried out to examine the role of lncRNA GHET1 in cancers, which reveal that lncRNA GHET1 is dysregulated in multiple cancers and that it plays an important role in tumor growth, metastasis, and invasion, as well as poor patient survival." (PMID 32908508, 2020). "Since the role of the hypoxic tumor microenvironment in chemotherapy failure has been increasingly considered in GC and other tumors recently, this might be a further direction to study the mechanism of lncRNA GHET1 regulating tumor drug resistance." (PMID 32908508, 2020). "lncRNA GHET1 may affect tumor metastasis and prognosis; however, a majority of existing studies are limited by their small sample sizes and discrete outcomes." (PMID 32908508, 2020). "When compared with low lncRNA GHET1 expression, high lncRNA GHET1 expression was related to larger tumor size (P<0.01), worse differentiation (P<0.01), earlier distant metastasis (P=0.02), earlier lymph node metastasis (P<0.01) and more advanced clinical stage (P<0.01)." (PMID 31227613, 2019). "Nevertheless, high lncRNA GHET1 expression was obviously related to larger tumor size (P<0.01), worse differentiation (P<0.01), earlier distant metastasis (P=0.02), earlier lymph node metastasis (P<0.01) and more advanced clinical stage (P<0.01) than low lncRNA GHET1 expression in cancers." (PMID 31227613, 2019). "Collectively, lncRNA GHET1 participates in the development and progression of tumours and may serve as a promising biomarker for prognosis in Asian with cancers." (PMID 31251476, 2019). "As a result, GHET1, IGF2BP2 and E2F6 presented elevated expression in CC tissues compared with non-tumor tissues." (PMID 31682716, 2020). "Among them, HOTAIR, PVT1, H19, MALAT1, GHET1 and HULC were significantly higher in tumor tissues compared with control tissues." (PMID 26096073, 2015). "Furthermore, lncRNA GHET1 knockdown decreased HIF-1α expression in hypoxia and significantly inhibited tumor development in vivo." (PMID 33869194, 2021). "Moreover, up-regulation of GHET1 expression predicted larger tumor size, positive lymph node metastasis, positive distant metastasis, and advanced TNM (tumor-node-metastases) stage in human cancers." (PMID 32280301, 2020). "The reason may be that lncRNA GHET1 is closely related to P21, c-Myc, WNT, and other tumor proliferation, invasion, and prognosis molecular markers." (PMID 32908508, 2020). "However, the function of E2F6 in CC tumor progression and its relation with GHET1 have never been explored." (PMID 31682716, 2020). "However, we did not observe any correlation between GHET1 expression and other clinicopathological parameters including age, tumor size, and histological type." (PMID 30948501, 2019).